PLGLB1 (plasminogen like B1)
Description:
May bind noncovalently to lysine binding sites present in the kringle structures of plasminogen. This may interfere with the binding of fibrin or alpha-2-antiplasmin to plasminogen and may result in the localization of activity at sites necessary for extracellular matrix destruction.
Synonyms: PLGL; PRGB; PLGP1; PRP-B
Gene: Protein-coding gene on chromosome 2 (86,996,231 to 87,021,852, reverse strand). Ensembl gene ENSG00000183281.
Subcellular location: Secreted
Subcellular location (Human Protein Atlas): Vesicles; Predicted to be secreted
Gene Ontology:
Cellular component: extracellular region
Homologues: Paralogues in human: PLGLB2 (100% identical), PLG (96% identical), PRSS50 (11% identical), PRSS33 (10% identical), PLAT (9% identical), OVCH1 (8% identical), TMPRSS12 (6% identical), KLK9 (5% identical), PRSS27 (5% identical), GZMM (4% identical), KLK15 (4% identical), PRSS48 (4% identical), and 2 more.
Diseases named in the same sentence as PLGLB1 in open-access papers:
PLGLB1 is named in the same sentence as 7 diseases in open-access papers, as found by Europe PMC text mining. Sharing a sentence is not in itself a finding about the gene and the disease. The quoted sentences say what the papers report.
COVID-19 (1 paper, 2022). A disease caused by infection with severe acute respiratory syndrome coronavirus 2. "The higher serum level of PLGLB1 in COVID-19 patients than in control groups was further confirmed by parallel reaction monitoring (PRM)." (PMID 35958562, 2022). "The results showed that the serum level of PLGLB1 was significantly higher in COVID-19 patients than that in the controls." (PMID 35958562, 2022). "In this study, we found that the serum level of PLGLB1 could stably differentiate COVID-19 patients (ranging from one day to 4 months after diagnosis) from uninfected individuals with high accuracy." (PMID 35958562, 2022). "Among them, plasminogen-like protein B (PLGLB1, also known as PRP-B) exhibited the most pronounced trend that kept a high level in COVID-19 patients, and its level was even increased at the convalescence stage (time-point 3) compared with the early stage (time-point 1)." (PMID 35958562, 2022). "It was interesting that PLGLB1 not only maintained a higher level during the three stages of COVID-19 compared with healthy controls, but also increased in all severity groups (including the asymptomatic group) compared with non-COVID-19 controls." (PMID 35958562, 2022). "Parallel reaction monitoring (PRM) validation of PLGLB1 was further performed in 24 serum samples (18 COVID-19 samples and 6 controls, including 17 new samples not included in the TMT experiment)." (PMID 35958562, 2022).
tumor (2 papers, 2022 to 2025). "Our results also revealed a putative CTC-537E7.3/miR-190b-5p/PLGLB1 ceRNA circuit, which may contribute to tumor progression in HCC." (PMID 40729031, 2025). "Additionally, our ceRNA analysis indicates that CTC-537E7.3 acts as a sponge for the oncogenic miR-190b-5p, thereby leading to repression of PLGLB1; perturbation of this axis may enhance PLGLB1 expression and drive tumor progression." (PMID 40729031, 2025). "Moreover, a dedicated competitive endogenous RNAs (ceRNAs) analysis suggested that CTC-537E7.3 may act as a molecular sponge for the tumor-suppressive miR-190b-5p, thereby relieving post-transcriptional repression of the oncogenic effector PLGLB1." (PMID 40729031, 2025).
PLGLB1 also shares sentences with these, for which no sentence is quoted: asthma (1 paper); cancer (1); cystic fibrosis (1); prion disease (1); scrapie (1).